RAG1 (recombination activating 1)
Diseases named in the same sentence as RAG1 in open-access papers (continued):
Sharing a sentence is not in itself a finding about the gene and the disease.
tumor (continued). "Vector controls or CT26-CXCL10 cells (pools of three clones each), were implanted in immune-competent hosts, as well as in immune-deficient Rag1-/- mice (respectively), and tumor formation was monitored after 35 days." (PMID 29163806, 2017). "To confirm this causality, we evaluated the effect of Symbioflor-2 on CT26 tumor development in Rag1−/− mice." (PMID 26981777, 2016). "Moreover, these tumour cells displayed heightened expression of genes associated with early B‐cell development, including Rag1/2, Endou, and Dntt." (PMID 40887856, 2025). "Surprisingly, tumor response to cytokine-armed DCPs was conserved in both Rag1-deficient and immunocompetent mice with depleted T cells, suggesting that T cell cytotoxicity may be dispensable for antitumor immunity." (PMID 37996514, 2024). "To test whether SLC38A2 acts in a tumour-intrinsic manner or requires the immune system for its in vivo effects, we examined growth of SLC38A2-deficient MC38 tumours in Batf3–/– or Rag1–/– mice." (PMID 37407815, 2023). "IMQ upregulated interferon γ (IFN-γ) expression in CD8+ T cells in both the lymph nodes and the tumor, and the antitumor effect was abolished in both Rag1-deficient mice and IFN-γ-deficient mice, indicating that IFN-γ produced by CD8+ T cells play a crucial role in the IMQ-induced antitumor effect." (PMID 34439104, 2021). "In order to elucidate whether Aid is indeed functional prior to pre-BCR expression, we developed an Aid-deficient mouse model with a tumor prone Rag1-/- background (p19Arf-/-Rag1-/-Aid-/- ARA)." (PMID 29100269, 2017). "To determine whether adaptive immune responses are involved in Cxcl14-mediated tumor suppression, we examined the tumor growth from these clones in Rag1-deficient C57BL/6 mice (Rag1−/−)." (PMID 27143385, 2016). "Interestingly, when this setting was used, greater anti-tumor activity was observed for the Fc-LS variants tested in hFcRn/Rag1−/− tumor xenografted mice, showing a positive correlation between FcRn-binding enhancement and in vivo efficacy." (PMID 25699055, 2015). "Moreover, IL-23-deficient mice are resistant to tumor formation, and the depletion of ILCs and IL-22 can reverse established tumors in a Rag1−/− mouse tumor model induced by Helicobacter hepaticus oral infection, indicating that ILCs and IL-22 are essential for the formation of colonic tumors." (PMID 31781671, 2019). "Our results provide evidence that both Xkr8 and TMEM16F knockout tumor cells suppress in vivo tumor growth in immunocompetent mice but in NOD/SCID or RAG1 immunoincompetent mice." (PMID 40391322, 2025). "To examine the dependence of an immune component in the tumor immune microenvironment, we compared the immunocompetent background above with NSG and RAG1 immune deficient mouse models." (PMID 40391322, 2025). "The loss of pro-tumorigenic effects of CSE in Rag1-KO and CD8-KO mice, along with the failure of smoke-FMT to increase tumor growth in Rag1-KO mice, suggests the need for functional adaptive immunity for CSE dysbiosis to promote tumor growth." (PMID 40104059, 2025). "To examine the dependence of an immune component in the tumor immune microenvironment, we compared the immunocompetent background above with NSG and Rag1 KO immune-deficient mouse models." (PMID 41198619, 2025). "Next, we performed a similar experiment in a competitive setting, wherein CD45.1+CD45.2+ KCa.3.1WT and CD45.1+ KCa.3.1R350A-expressing OT-I CD8+ T cells were mixed at a 1:1 ratio and transferred into B16-OVA tumor-bearing Rag1−/− mice." (PMID 40702340, 2025). "We performed RNA sequencing (RNA-seq) of day 9 TIL from T cells originally activated for 30 min in 0.1 mM or 0.03 mM Met and then cultured in 0.1 mM Met for 24 h before transfer into B16-OVA tumor-bearing Rag1−/− mice." (PMID 40702340, 2025). "The Rag1−/− cohort reconstituted with Pd1−/− Treg cells showed significantly enhanced tumor growth compared with those reconstituted with WT Treg cells." (PMID 40457060, 2025).
tumor (continued). "To assess the impact of STAT2 and IFNAR1 loss on tumorigenicity, we implanted each cell line subcutaneously into immunodeficient Rag1 KO mice and monitored tumor growth over time." (PMID 41440237, 2025). "In contrast, Usp22 suppression only resulted in a modest reduction in RM1 tumor growth both in RAG1 KO mice, as well as in vitro." (PMID 41252204, 2025). "We then activated OT-I T cells in 0.1 mM or 0.03 mM Met with either dimethylsulfoxide (DMSO) or TRAM-34 for 30 min, washed and cultured cells for an additional 24 h in 0.1 mM Met before transferring into B16-OVA tumor-bearing Rag1−/− mice." (PMID 40702340, 2025). "Our preliminary efficacy study of 5 in subcutaneous xenografts of U87 cells in Rag1 mice showed that 7 mg/kg, administered twice i.p., strongly inhibits tumor growth." (PMID 41471777, 2025). "The tumor-suppressing activity of DMAMCL is completely abolished in tumor-bearing C57BL/6 mice with homozygous Rag1 knockout, which prevents the formation of mature B and T cells." (PMID 39857717, 2025). "While less pronounced in the Rag1‐KO background, a similar trend of decreased and increased tumor growth was observed in the mice transferred with RARα‐KO T cells and RARα‐TG T cells." (PMID 40068101, 2025). "Using the same Rag1−/− tumor model, we found that CD30 frequency was significantly increased in Treg cells but not in CD45.1+ Teff cells among TILs." (PMID 40457060, 2025). "The tumor-promoting effect of the smoke-exposed dysbiotic gut microbiome was abrogated in Rag1-KO mice." (PMID 40104059, 2025). "In the orthotopic mouse model, p-FAK, p-STAT3 and IL-4 were significantly decreased in tumor tissues of Postn-/-Rag1-/- mice compared to Postn+/+Rag1-/- mice." (PMID 38773979, 2024). "Immunohistochemical staining, western blot, qRT-PCR and ELISA analyses further confirmed that IL-4 was significantly down-regulated in the tumor tissues of Postn-/-Rag1-/- injected with IHH-4 cells compared to their Postn+/+Rag1-/- counterparts." (PMID 38773979, 2024). "The tumor weight and volume measurements showed that Rab37 KO CD8+ T cells suppressed the LLC tumor growth in the Rag1-deficient mice." (PMID 38321486, 2024). "Postn-/-Rag1-/- mice exhibited significantly reduced tumor growth and decreased tumor weight compared to Postn+/+Rag1-/- mice." (PMID 38773979, 2024). "The protein and mRNA levels of cell proliferation marker Cyclin D1 were lower in the tumor tissues of Postn-/-Rag1-/- mice than those in Postn+/+Rag1-/- mice." (PMID 38773979, 2024). "Rag1−/− mice receiving transferred WT CD8+ T cells had a more decreased tumor growth rate and exhausted T cells compared to Rag1−/−NcDase−/− mice receiving transferred WT CD8+ T cells." (PMID 38302493, 2024). "Tumor growth was faster in Rag1 KO mice, suggesting T- or B-cell involvement in the control of tumor growth." (PMID 38927950, 2024). "We co‐transplanted parental 9609 tumour cells with vehicle control (PBS), MEK1‐low, or MEK1‐hi EVs into WT or RAG1−/− mice and monitored tumour growth." (PMID 39330930, 2024). "To interrogate the role of adaptive immunity more rigorously, we challenged Rag1–/– mice with B16 tumor cells, followed by treatment with r3LCMV." (PMID 38861331, 2024). "Decreased TNF-α and IFN-γ expression was observed in adoptively transferred tumor-infiltrating CD8+ T cells in Rag1−/− mice challenged with Id2fl/flCd4-Cre+ CD8+ T cells plus Id2fl/flCd4-Cre− CD4+ T cells." (PMID 38287103, 2024). "First, tumour‐bearing Rag1−/− mice were first established by engrafted with 1.0 × 105 B16F10‐OVA cells via subcutaneous injection." (PMID 36592612, 2023). "The results indicated that hSAAs/mSAAs-/-Rag1-/- mice had more metastatic tumor cells in the lungs than mSAAs-/-Rag1 -/- mice." (PMID 37620307, 2023). "On Day 12, Rag2−/−‐OT1‐iT cells (1.0 × 107/mouse) which were derived from the spleens of Rag1−/− recipients transplanted with day21‐iHPCs for 6 weeks, were retro‐orbitally to these tumour‐bearing mice." (PMID 36592612, 2023).
tumor (continued). "We observed a declined tumor growth and an enriched tumor-infiltrating lymphocytes in E0771-GD-WT group of wild-type mice, but not in E0771-GD-S46D group of wild-type mice or all groups of Rag-1-/- mice." (PMID 37495617, 2023). "Lungs were collected from NP- or saline-treated BALB/c and RAG1-KO mice 21 days after tumor inoculation." (PMID 36479083, 2022). "To further assess the mechanism of anti-tumor immunity, we measured WT, Gcc2KO and Rab14KO B16 tumor growth in either Rag1−/− or Ifnar1−/− mice." (PMID 36379959, 2022). "We found that Whsc1 ablation greatly expedited tumor growth, whereas KO of Whsc1 had minimal effects when tumor cells were engrafted into Rag1-null immunocompromised mice, suggesting that T cells are required for WHSC1 functions." (PMID 35230972, 2022). "Consistent with that notion, intratumoral doxorubicin administration reduced tumor growth in WT mice but therapeutic benefit was reduced in Rag1–/– mice which lack T and B cells." (PMID 36162919, 2022). "Along with high KRAS mutation rates and RAS84 expression, RAG-1 was characterised by STK11/LKB1 mutations (KL tumours) and RAG-4 by CDKN2A mutations (KC tumours)." (PMID 36163168, 2022). "Although chemoablation of nociceptor neurons with resiniferatoxin (RTX) reduced tumour growth in B16F10-inoculated wild-type mice, we found that naive OT-I CD8+ T cells enhanced tumour shrinkage when transplanted in RTX-exposed Rag1−/− mice." (PMID 36323780, 2022). "The tumor inhibition effect was also confirmed on the more aggressive HPV18-E7 HeLa tumor xenografts in Rag1 mice, where tumor volumes were monitored for 46 days." (PMID 36139356, 2022). "As a result, GK1 tumour‐bearing Rag1–/‐ mice that received Pdia4–/– T and B cells had better survival than those that received WT T and B cells." (PMID 35170261, 2022). "Tumor-bearing RAG1 KO mice were treated with ACPP-MMAE and IR in an identical regimen used in tumors grown in WT mice." (PMID 35790753, 2022). "To further validate the role of T cells, we isolated splenic T cells from vaccinated tumor-bearing mice and adoptively transferred them into immunocompromised Rag-1-/- mice, followed by tumor challenge." (PMID 36569934, 2022). "Tumor growth in Rag-1-/- mice demonstrated a significant reduction in tumor size only when the transferred T cells were obtained from the vaccinated mice." (PMID 36569934, 2022). "HT-29 cells were injected subcutaneously into Rag1−/− mice, and tumor development was monitored over time." (PMID 35022391, 2022). "We describe the impact of the adaptive immune system on tumor growth and treatment response using Rag1 knockout mice." (PMID 35309309, 2022). "We confirmed that efficient tumor control following each therapy requires an immunocompetent host as efficacy was markedly reduced in Rag1–/– compared with WT mice." (PMID 36162919, 2022). "Accordingly, GK1 tumour‐bearing Rag1–/‐ mice that received Pdia4–/– T and B cells had smaller tumour volume and tumour weight than those that received WT T and B cells." (PMID 35170261, 2022). "We found that Rag1−/− and Rag2−/−γc−/− mice had increased tumour growth and size, and reduced survival compared with wild-type controls, in accordance with previous reports." (PMID 33535624, 2021). "The results showed that the use of anti-PVRIG mAb significantly inhibited tumor growth in Rag1−/− mice compared to those treated with control antibody (P < 0.001), suggesting that anti-PVRIG mAb was effective even in the absence of adaptive immunity." (PMID 34174928, 2021). "We also found that INMT-KD DU145 cells grew tumor much slower than control cells in Rag1−/− male mice." (PMID 34587977, 2021). "Despite having the same size, B16F10 tumors growing in Rag1–/–Clec9agfp/gfp mice contained more tumor-infiltrating cDC1s when compared with Rag1–/– controls, whereas numbers of cDC2s were similar." (PMID 33980589, 2021).
tumor (continued). "These beneficial therapeutic effects of αPD1 + αGITR were also observed in Rag1–/– mice after adoptive transfer of Treg cells plus CD8 T cells followed by orthotopic inoculation with CT2A tumor cells." (PMID 33976133, 2021). "Again, the protection from tumor growth in the MIC-1fms group was reversed when these mice were also immunodeficient because of concurrent Rag1 gene deletions." (PMID 32502202, 2020). "We found that the anti-tumor effect of Arf1 knockdown in wild-type mice was lost in both the Rag1-KO and INFγ-KO mice." (PMID 31924786, 2020). "We then engrafted E.G7-OVA tumor cells into the groin of the Rag1−/− or OT1-iT-reconstituted Rag1−/− mice (OT1-iT-Rag1−/− mice) by subcutaneous injection (0.2 million/mouse)." (PMID 31729468, 2020). "Tumor growth kinetics demonstrated that the E.G7-OVA tumors were dramatically inhibited in the OT1-iT-Rag1−/− mice in comparison with the control Rag1−/− mice." (PMID 31729468, 2020). "The expression of cytokines (e.g., C-C motif chemokine ligand 2 (CCL2)) that facilitate mammary tumor metastasis was also examined using tumor-free and 4T1-mCh tumor-bearing Rag1−/− mice." (PMID 33628730, 2020). "We also assessed the anti-tumor activity of the indicated therapeutics in RAG1 KO mice bearing B16-OVA tumors." (PMID 31511064, 2019). "Tumor growth in WT mice was inhibited by Erb-sumIL2, but the therapeutic effect of Erb-sumIL2 was abolished in Rag1 KO mice despite a high percentage of NK cells, revealing that therapeutic effect of Erb-sumIL2 requires adaptive immunity." (PMID 31462678, 2019). "In both immune competent and Rag1/2-deficient mice, tumor cells engineered to express IL-35 exhibited increased myeloid cell accumulation in the TME resulting in increased tumor angiogenesis." (PMID 31681561, 2019). "Due to a homozygous Rag1 gene deletion, this model lacks mature T and B lymphocytes; therefore, it can be used for human tumor xenograft and cancer cell implant studies." (PMID 30636104, 2019). "Next, to explore the potential role of adaptive immunity in chemerin-dependent EMT6-tumor growth suppression, we used Rag1 KO mice, which lack mature T and B cells." (PMID 31139180, 2019). "As expected, the tumor growth was significantly faster (two-tailed unpaired Student’s t-test, p-value of 0.019) in RAG1−/− mice compared with the wild-type mice." (PMID 29296022, 2018). "To test the interaction between lymphoid populations in this experimental model, we designed an experiment model where we transferred T and B lymphocytes or DCs from C57Black/6 mice to TC-1 tumor bearing RAG1-/- mice." (PMID 29975708, 2018). "We demonstrated that the anti-tumor effect of macrophage MGLL was largely attenuated in Rag1 knockout mouse, indicating an adaptive immunity dependent manner was involved." (PMID 29968710, 2018). "Stimulated or control DCs from tumor bearing donors transplanted into RAG1-/- mice together with T cells also from tumor bearing donors were unable to inhibit tumor growth (Tumor T/control tumor DC and Tumor T/CD40 tumor DC)." (PMID 29975708, 2018). "Syngeneic transfer of LMP2A/MYC primary tumor cells into Rag1 knockout mice (Rag1KO mice) leads to tumor development and splenomegaly in the recipient Rag1KO mice within a few weeks." (PMID 30135222, 2018). "We inoculated wild type mice, RAG1-/- mice and BKO mice (B lymphocytes deficient) with 1.5x104 TC-1 cells and observed the tumor growth kinetics." (PMID 29975708, 2018). "We expect that, as tumor grew larger the myeloid APCs in the RAG1-/- mice would be modulated by the tumor and inhibit T cells." (PMID 29975708, 2018).
tumor (continued). "Compared to low-fat chow-fed Rag1−/− mice, HFD-fed Rag1−/− mice developed tumours earlier, and exhibited increased tumour growth over time and decreased survival to ethical endpoint." (PMID 28352127, 2017). "LNCaP xenograft tumours were palpable 8 weeks earlier in Rag1−/− HFD-fed mice than low-fat chow-fed Rag1−/− mice and tumours exhibited more rapid growth." (PMID 28352127, 2017). "Tumor size, multiplicity and incidence were reduced in Rag1-/- hosts implanted with CXCL10-expressing cells, as compared to control CT26 cells, but the differences did not attain significance." (PMID 29163806, 2017). "We found that conditionally expressing mutant Kras, using Rag1-Cre, gave rise to CNS haemangioblastoma in the cortex and cerebellum in mice that present with highly vascular tumours with stromal cells similar to human haemangioblastomas." (PMID 28322325, 2017). "Control CD8+ T cells and Rik-overexpressing CD8+ T cells were periodically transferred into recipient Rag1−/− mice that were bearing Hepa-1c1c7 tumor implants, respectively." (PMID 28382040, 2017). "When we intratumourally injected recombinant IL-21 (rIL-21) into MC38 H-2Kb and H-2Db KO tumour-bearing Rag1−/− mice, tumour growth was significantly inhibited with an increase in tumour-infiltrating NK cells." (PMID 28585539, 2017). "Both groups showed identical growth of the primary tumor, however CR-CaP tumor growth after castration was significantly delayed in mice reconstituted with Rag1−/− BM compared to WT BM." (PMID 27437104, 2016). "To determine the role of T cells in the antitumoral effect of AAV-mIL15 we repeated the experiment implanting MC38 tumors in RAG1−/− mice and tumor growth and survival was evaluated as previously indicated." (PMID 27356750, 2016). "Because tumor growth is only partially suppressed by Cxcl14 reexpression in Rag1−/− mice, our results indicate that both innate and adaptive immune responses play important roles in the antitumor functions of CXCL14." (PMID 27143385, 2016). "While αSlamf6 treatment causes a significant loss of leukemic cells in the blood and spleen of TCL1-192-bearing SCID mice, as well as LMP2A/λMyc bearing Rag1−/− mice, both tumor cells remain in the peritoneal cavity of the recipient animals." (PMID 27029059, 2016). "Mouse CRC cell line MC38 was injected endoscopically into the colonic submucosa of syngenic C57Bl/6 wild-type and RAG1-/- immunodeficient mice and the tumor growth was monitored weekly using endoscopy." (PMID 25853550, 2015). "Spleen cells from control and from B16-bearing Rag1-/- mice 21 days post tumor transplantation were incubated with brefeldin A for 5 h and analyzed by cytometry." (PMID 25101668, 2014). "Treatment of tumor-bearing C57BL/6 mice with vMyx-IL15Rα-tdTr resulted in longer survival than similarly treated RAG1-/- mice." (PMID 25329832, 2014). "The anti-tumor effect of vMyx-IL15Rα-tdTr in immunocompetent animals showed the same pattern as in RAG1-/- mice, with overall longer median survival in corresponding groups." (PMID 25329832, 2014). "Bycontrast, all 12 8101 tumor-bearing Rag1-/- C57BL/6mice rejected the established tumor when treated with spleen cells from youngmice that had been immunized with live 8101 cancer cells." (PMID 22415314, 2012). "A preliminary Rag1 xenograft study demonstrated that compound 5 effectively suppressed tumor growth without causing significant weight loss." (PMID 41471777, 2025). "To determine whether ablation of R350 methylation drives T cell exhaustion in tumors, we transferred T cells expressing KCa.3.1WT or KCa.3.1R350A into B16-OVA tumor-bearing Rag1−/− mice." (PMID 40702340, 2025). "Transduced OT-I CD8+ T cells were transferred into MC38-OVA tumor-bearing Rag1−/− mice." (PMID 40204636, 2025). "However, these tumor-suppressing effects vanished in RAG1 knockout mice, which lack functional T and B cells, underscoring the essential role of immune cells in mediating microbiota-driven tumor suppression." (PMID 40243755, 2025).